TSLP (thymic stromal lymphopoietin)
Diseases named in the same sentence as TSLP in open-access papers (continued):
Sharing a sentence is not in itself a finding about the gene and the disease.
endometriosis (6 papers, 2017 to 2025). The growth of functional endometrial tissue in anatomic sites outside the uterine body. "One study has focused on oxidative stress biomarkers and the subsequent impact on cardiovascular risk in endometriosis patients, such as elevated levels of pro-inflammatory cytokines like thymic stromal lymphopoietin (TSLP), TNF-α, and IL-1β." (PMID 40564779, 2025). "There is currently no reliable information available on the influence of IL25 and TSLP gene polymorphisms on cytokine levels in endometriosis." (PMID 39767772, 2024). "Unfortunately, there is limited specific information regarding the sensitivity and specificity of IL-25 and TSLP in diagnosing endometriosis." (PMID 39767772, 2024). "Increasing evidence suggests that interleukin-33 (IL-33) and TSLP levels are elevated in the peripheral blood, endometriotic endometrium, and peritoneal fluid of individuals with endometriosis." (PMID 39767772, 2024). "For example, thymic stromal lymphopoietin (TSLP) has been reported to be involved in the development of endometriosis, but α7nAChR has been shown to inhibit TSLP." (PMID 35658970, 2022). "TSLP also is expressed in the stroma of endometrioma tissues, and high TSLP concentrations are found in both the serum and peritoneal fluid of women with endometriosis, suggesting TSLP is involved in endometriosis." (PMID 33652749, 2021). "In endometriosis, TSLP is expressed in both stromal and epithelial cells, and its concentration in serum and peritoneal fluid from women with endometriosis has been reported to be elevated." (PMID 33381124, 2020). "In addition, our study provides more credence to the ReTIAR notion, since, through the ReTIAR lens, we can coherently piece together seemingly unrelated findings, such as TSLP overexpression, M2 macrophages, platelet aggregation, and the Th1/Th2 imbalance in endometriosis." (PMID 33381124, 2020). "This suggests that platelets can promote the proliferation or recruitment of Tregs in endometriosis, possibly through the secretion of TGF-β1 and the up-regulation of TSLP expression in endometriotic lesions." (PMID 33381124, 2020).
Hyperkeratosis (6 papers, 2010 to 2024). Hyperkeratosis is a histopathological term defining a thickened stratum corneum and may be present in many different skin conditions, with many possible overlaps. "Buccal mucosa specimens from patients with OLP, hyperkeratosis, and ulcer were analyzed by immunohistochemistry for expression of TSLP, its receptor (TSLPR), and inflammatory cells." (PMID 28278185, 2017). "BM specimens from patients with OLP, hyperkeratosis or ulcer were examined after immunohistochemical staining to evaluate the distributions of TSLP and TSLPR." (PMID 28278185, 2017). "Moreover, expression of TSLP was weakly detected in the epithelium from patients with hyperkeratosis, but was rarely seen in the lesions from patients with ulcer." (PMID 28278185, 2017). "This is evidenced by the effectiveness of anti-human TSLP antibodies in the mitigation of skin psoriasis hallmarks, including reduced skin thickness, erythema, scaling, epidermal hyperplasia and reduced histopathological skin lesions such as hyperkeratosis, acanthosis, and parakeratosis." (PMID 39726595, 2024). "TSLP was detected in/around the epithelium of patients with OLP and hyperkeratosis, whereas TSLPR, CD11c (mDC), and GATA3 (Th2) were strongly expressed in the subepithelial layer only in OLP patients." (PMID 28278185, 2017). "These hallmarks included epidermal acanthosis, spongiosis, hyperkeratosis, and parakeratosis, systemic type 2 cell expansion with a dramatic accumulation of CD4+ T cells, neutrophils, eosinophils and dermal mast cells, and elevation of serum IgE and TSLP levels." (PMID 24843010, 2014).
sensitization (6 papers, 2015 to 2022). "The polymorphism was further reproducibly associated with a DNA methylation signature in whole blood (P = 4.5x10-40) that also associated with allergic sensitization and expression in blood of the cytokine TSLP (P = 1.1x10-4)." (PMID 27149122, 2016). "Upon allergic sensitization in the human airways, epithelial cells encountering allergens can release thymic stromal lymphopoietin (TSLP) to attract, activate and polarize dendritic cells (DCs)." (PMID 26772182, 2016). "Importantly, we conclude from our study that IL-1β and TSLP are two independent factors promoting allergic sensitization and atopic march." (PMID 36050303, 2022). "The other 16 cytokines tested were not affected by diet or allergic sensitization (data not shown) except for TSLP, which was significantly upregulated in HFD mice compared to ND mice." (PMID 27483441, 2016).
systemic sclerosis (6 papers, 2017 to 2024). A chronic disorder, possibly autoimmune, marked by excessive production of collagen which results in hardening and thickening of body tissues. "Dysregulation of TSLP expression is closely related to immunopathology in several diseases, including RA and systemic sclerosis (SSc)." (PMID 38911857, 2024). "Platelets may also induce the lesional expression of thymic stromal lymphopoietin (TSLP) through platelet-derived IL-1β and drive type 2 immunity that facilitates lesional fibrogenesis, similar to how platelets induces endothelial TSLP expression to promote fibrogenesis in human systemic sclerosis." (PMID 36769489, 2023).
Erythema (5 papers, 2018 to 2025). Redness of the skin, caused by hyperemia of the capillaries in the lower layers of the skin. "In mice, both EGF and pimecrolimus—a topical calcineurin inhibitor—groups showed reduced erythema, inflammation, and expression of thymic stromal lymphopoietin (TSLP), a cytokine that plays a role in the pathogenesis of AD." (PMID 38202116, 2023). "In mice, both EGF and pimecrolimus groups showed less erythema with significantly reduced inflammation and decreased expression of thymic stromal lymphopoietin." (PMID 29862299, 2018).
keloid (5 papers, 2020 to 2026). An irregularly shaped, elevated mark on the skin caused by deposits of excessive amounts of collagen during wound healing. "This study revealed the significant pathological role of TSLP in keloid formation, suggesting it as a potential target for antifibrotic therapy in the future treatment of keloids." (PMID 41596210, 2026). "Given that TSLP expression is also greatly enhanced in keloid lesions, extending to uninvolved skin, it is meaningful to investigate whether TSLP also has a role in promoting fibrosis in keloids." (PMID 37895153, 2023). "Our results associate keloid tissues with an inflammatory milieu representing multiple T-helper pathways, including the Th2 (e.g. IL-4R, CCL11, TSLP, TNFSF4/OX40L, TNFRSF4/OX40), Th1 (e.g. IFNγ, CXCL10/11), Th17/Th22 (e.g. PI3, CCL20, S100As) axes, as well as the JAK/STAT signaling molecule JAK3." (PMID 33329590, 2020). "Moreover, decreasing the level of thymic stromal lymphopoietin may be crucial for treating keloids." (PMID 40330546, 2025). "Given the significantly increased expression of TSLP in non-lesional keloid skin, exploration of tezepelumab, an anti-TSLP monoclonal antibody, may also be warranted." (PMID 33329590, 2020).
ovarian carcinoma (5 papers, 2019 to 2025). A malignant neoplasm originating from the surface ovarian epithelium. "TSLP was overexpressed in ovarian cancer and associated with poor prognosis." (PMID 40873585, 2025). "In ovarian cancer, the expression of TSLP mRNA was significantly higher in tumour tissues and cancer cell lines than the normal controls." (PMID 33652749, 2021). "Compared with adjacent normal tissues, TSLP mRNA levels determined by real-time PCR were significantly higher in human ovarian cancer tissues (n=27), (P<0.001), implying the potential function of TSLP in ovarian cancer." (PMID 31023965, 2019). "In the present study, we investigated mRNA levels in two well-known ovarian cancer cell lines and examined expression patterns of TSLP in a large amount of tissue samples obtained from EOC patients." (PMID 31023965, 2019). "We, therefore, assumed that TSLP might be involved in the ovarian carcinoma and could serve as a biomarker or as a therapeutic target." (PMID 31023965, 2019). "Our statistical analyses showed that TSLP overexpression could be used as a prognostic marker and indicator of poor prognosis in ovarian cancer patients." (PMID 31023965, 2019). "Supplementarily, TaqMan TSLP expression assays (Hs00263639_m1) targeted all 3 transcript variants (TSLPv1, TSLPv2 and TSLPv3) also resembled the expression patterns, thus indicating TSLPv2 (sfTSLP), but not TSLPv1 (lfTSLP) nor TSLPv3 (non-coding RNA), was expressed in human ovarian cancer cells." (PMID 33652749, 2021). "We treated the TSLP-negative human ovarian cancer cell lines (A2780, IGROV-1, KURAMOCHI and TOV21G) with DNA methyltransferase inhibitor (5-aza-2′-deoxycytidine; AZA), histone deacetylase (HDAC) inhibitor (Trichostatin A; TSA) or histone methyltransferase (HMTase) inhibitor (BIX01294)." (PMID 33652749, 2021).
rhinitis (5 papers, 2017 to 2022). An inflammation of the mucous membrane lining the nose, usually associated with nasal discharge. "In particular, alarmin cytokines such as IL-25, IL-33, and TSLP are strongly associated with the development of rhinitis due to PM exposure." (PMID 35378908, 2022). "In this form of rhinitis, aeroallergen components of mold fungi can in addition lead to macrophage and T cell activation that can be observed as an increased level of factors such as TSLP and GM-CSF in the local cytokine profile of these patients." (PMID 29109963, 2017).
thymoma (5 papers, 2017 to 2024). A neoplasm arising from the epithelial cells of the thymus. "Since TSLP has a prominent role in the regulation of thymic cell lineages, these data suggested a contribution of miR-19b-5p to T cell dysregulation and Treg deficiency in the thymomas of MG patients." (PMID 39329732, 2024). "In a separate study, the expression of miR-19b-5p, which targets thymic stromal lymphopoietin (TSLP), was elevated in MG-related thymomas." (PMID 32587589, 2020). "This approach was not successful, however, in the NOG background, as our NOG transgenic strain expressing the human TSLP gene, which possesses about 42% homology with the mouse TSLP gene, developed severe thymoma, which resembled the disease frequently seen in NOD-scid mice (data not shown)." (PMID 29387068, 2017). "An increased expression of hsa-mir-19b-5p was observed in thymomas from TAMG patients, and cell culture investigations revealed that this miRNA targets the thymic stromal lymphopoietin (TSLP), an interleukin-7-like cytokine involved in the development and maturation of T cells." (PMID 36672310, 2023). "The negative correlation with TSLP mRNA contributes to T-cell imbalance and promotes MG-related thymoma development." (PMID 32587589, 2020). "Further investigation of the regulatory mechanisms governing aberrant expression of TSLP found the increased presence of miR-19b-5p in all thymoma patients compared with healthy controls, with a significant difference in levels between TAMG patients and thymoma patients without myasthenia gravis." (PMID 38254905, 2024).
allergic contact dermatitis (4 papers, 2014 to 2024). An inflammatory skin condition caused by an immune response to direct contact between the skin and an allergen. "Likewise, in mice, TSLP expression in the skin is increased in a model of FITC-induced allergic contact dermatitis, whereas TSLPR−/− mice are resistant to disease development." (PMID 24498391, 2014). "Non-histaminergic itch is additionally important in allergic contact dermatitis potentially mediated via thymic stromal lymphopoietin (TSLP)." (PMID 31973112, 2020).
Arthritis (4 papers, 2012 to 2022). Inflammation of a joint. "TSLP and IL-7 have an additive effect on the production of Th17-cytokines in a human in vitro model, and enhance arthritis in mice linked with enhanced inflammation and immunopathology." (PMID 26110994, 2015). "Adoptive transfer of adequate ILC2s to arthritis models, in which the isolated cells were expanded in vitro through stimulation using cytokines such as IL-2, IL-7, IL-25, IL-33, and TSLP, mitigated experimental arthritis." (PMID 35163028, 2022). "We here investigated the effects of simultaneous blocking of TSLP and IL-7 activity in murine experimental arthritis and studied their combined effects in in vitro DC + T-cell co-cultures using RA patient material." (PMID 26110994, 2015). "Our group previously demonstrated that IL-7 and TSLP separately play a pro-inflammatory role in experimental murine arthritis." (PMID 26110994, 2015). "Block of TSLP reduced the severity of collagen-induced arthritis." (PMID 23190696, 2012). "Though both IL-7 and TSLP induce T-cell activation and proinflammatory cytokine production via different target cells while signalling through the same receptor subunit, their combined effects have not been studied in arthritis." (PMID 26110994, 2015).
atopic march (4 papers, 2021 to 2023). sequential manifestations of different allergic diseases such as eczema, asthma and rhinitis. "In addition, the association of the development of atopic march with abnormal skin barrier function (e.g., due to filaggrin gene mutations) and epithelial cell (EC)-derived cytokines, such as thymic stromal lymphopoietin (TSLP), interleukin (IL)-33, and IL-25, has been suggested." (PMID 34828780, 2021). "In addition, keratinocyte TSLP can trigger the atopic march in mice, and mice overexpressing TSLP in keratinocytes showed a spontaneous AD-like phenotype, with the development of eczematous lesions, increased circulating Th2 cells, and higher serum IgE levels." (PMID 38053996, 2023).
cutaneous T-cell lymphoma (4 papers, 2019 to 2025). "TSLP mRNA is overexpressed in lesional skin and cutaneous T-cell lymphoma (CTCL)." (PMID 40873585, 2025).
periodontitis (4 papers, 2021 to 2024). An acute or chronic inflammatory process that affects the tissues that surround and support the teeth. "Moderate-to-severe AD was positively associated with the GCF levels of IL-31 and TSLP, whereas severe periodontitis was negatively associated with IL-31 (p < 0.05)." (PMID 37958576, 2023). "Moreover, a study reported a detection frequency of 5.9% for TSLP in inflamed periodontal sites of patients with gingivitis and 9.1% in inflamed periodontal sites of patients with periodontitis." (PMID 37958576, 2023). "The role of TSLP in periodontal tissues remains unclear; nonetheless, it is possible that the cytokine participates in periodontitis progression." (PMID 37958576, 2023). "Therefore, this study aims to compare the GCF levels of IL-13, IL-31, and TSLP between AD patients and healthy controls and to explore the impact of periodontitis and AD on the GCF levels of these molecules." (PMID 37958576, 2023). "In addition, we also showed that AD and periodontitis influence IL-31 in opposing and independent ways, while TSLP levels are only influenced by AD diagnosis." (PMID 37958576, 2023). "A number of these genes were also significantly increased in aging and periodontitis tissues (e.g., ANXA1, HMGB1, S100A8, S100A9, APOE/ß2-GPI, LTF, TSLP)." (PMID 38098978, 2023). "A multiple regression analysis was performed to evaluate the impact of AD diagnosis and the covariates age, gender, smoking status, and periodontitis severity on the GCF levels of IL-13, IL-31, and TSLP." (PMID 37958576, 2023).
airway allergies (3 papers, 2019 to 2025). "Basal-cell hyperplasia, which is commonly associated with allergic respiratory disease, is correlated with the basal-cell production of alarmins such as IL-33 and TSLP, as well as with IL-4/IL-13-induced gene signaling in basal cells." (PMID 39653767, 2025). "The findings were expanded in a murine airway allergy and the CR model study, in which the inhibition of livin or TSLP significantly attenuated airway allergic response and the CR development." (PMID 34131408, 2021). "Depletion of livin or inhibiting TSLP attenuates CR development and inhibits airway allergy, this has the translational potential to be used in the treatment of airway allergy." (PMID 34131408, 2021). "Depletion of livin or inhibition of TSLP markedly attenuated CR and airway allergy." (PMID 34131408, 2021).
chronic spontaneous urticaria (3 papers, 2023 to 2024). "Chronic spontaneous urticaria is characterized by increased levels of IL-25, IL-33, and TSLP, indicating the possible involvement of ILC2s." (PMID 38474426, 2024). "Because it is known that TSLP induces mast cell development, prevents apoptosis in skin mast cells and it is markedly upregulated in the wheals of patients with chronic spontaneous urticaria, the anti-TSLP monoclonal antibody tezepelumab is undergoing clinical trial assessments for this disease." (PMID 37628907, 2023).
coeliac disease (3 papers, 2016 to 2021). "Whilst TSLP isoforms are reported to be responsible for two opposite immune functions, both their expressions in the duodenal mucosa of patients with coeliac diseases (CD) were shown to be decreased in active CD mucosa." (PMID 33652749, 2021). "Abnormal thymic stromal lymphopoietin expression in the duodenal mucosa of patients with coeliac disease." (PMID 26744619, 2016). "The expression of epithelial-derived thymic stromal lymphopoietin (TSLP), a key cytokine modulator of gut immune tolerance, may be dysregulated in coeliac disease (CD)." (PMID 26744619, 2016).
colorectal cancer (3 papers, 2020 to 2025). A primary or metastatic malignant neoplasm that affects the colon or rectum. "We will also discuss recent findings demonstrating that an anti-TSLP monoclonal antibody (mAb) can exert a protective effect in a mouse model of colorectal cancer." (PMID 40873585, 2025). "TSLP expression correlated with poor prognosis in colorectal cancer (CRC)." (PMID 40873585, 2025). "Finally, an anti-tumor role for TSLP was reported in colorectal cancer, where its expression in the tumor was significantly lower than in surrounding tissues, and negatively correlated with clinical staging in colorectal cancer patients." (PMID 33042121, 2020).
endometrial cancer (3 papers, 2021 to 2025). Primary or metastatic malignant neoplasm involving the endometrium (mucous membrane that lines the endometrial cavity). "The authors concluded that the loss of TSLP in endometrial gland epithelial cells may contribute to endometrial cancer development." (PMID 40873585, 2025). "A recent study reported that the expression of TSLP (measured by Western blot) was reduced in several human endometrial cancer cell lines compared to normal human endometrial cells." (PMID 40873585, 2025). "Overexpression of sfTSLP in TSLP ovarian and endometrial cancer cells promoted tumor growth in vitro." (PMID 40873585, 2025). "Although sfTSLP transcription was up-regulated significantly in TSLP-positive (with low expression levels) human endometrial cancer cell (KLE) after AZA treatment, the promoter DNA methylation was rarely detected in KLE cells with the treatment of AZA or DMSO." (PMID 33652749, 2021). "Micrograms of TSLP partially inhibited the proliferation of two endometrial cancer cell lines." (PMID 40873585, 2025). "Besides, we used the two polyclonal anti-TSLP antibodies to examine the protein expression of total TSLP in ovarian/endometrial cancer tissues by immunohistochemistry." (PMID 33652749, 2021). "On the other hand, silencing EZH2 histone methyltransferase downregulates the TSLP expression in oesophagus squamous cell carcinoma cells, which supports our observation that histone methylation regulated sfTSLP transcription in KLE human endometrial cancer cells." (PMID 33652749, 2021).